ETV1 (ETS variant transcription factor 1)
Diseases named in the same sentence as ETV1 in open-access papers (continued):
Sharing a sentence is not in itself a finding about the gene and the disease.
adenocarcinoma (5 papers, 2010 to 2020). A common cancer characterized by the presence of malignant glandular cells. "Previously, we published data on ETV1 and MK2 expression in adenocarcinomas of the esophago-gastric junction, showing that nuclear overexpression of ETV1 was associated with significantly better patients OS." (PMID 31527546, 2019). "The ETV1 expression level was low in general among both the adenocarcinomas and the synchronous small GISTs." (PMID 33335133, 2020). "A further notable finding that all the three ETV1-negative GISTs were associated with ETV1 negativity of the synchronous adenocarcinoma as well (with strong ETV1 expression of the ICCs as internal positive control)." (PMID 33335133, 2020). "We have also investigated the immunohistochemical expression of the ETV1 in the synchronous GISTs and adenocarcinomas since it was described as a transcription factor responsible for the differentiation of the interstitial cells of Cajal and to cooperate with KIT to promote GIST tumorigenesis." (PMID 33335133, 2020). "However, progression to the adenocarcinoma stage is stifled in these mice, suggesting that inhibitory pathways possibly preclude ETV1 from exerting its full oncogenic potential." (PMID 31160676, 2019). "One unresolved question is why ETV1 transgenic mice did not progress from PIN to the adenocarcinoma stage." (PMID 31160676, 2019).
prostate (4 papers, 2015 to 2025). "Taken together, these results place EGFR as a mediator of ETV1 oncogenic activity both in early and advanced prostate carcinogenesis, while ERG overexpression seems to indirectly repress EGFR activation in early PCa carcinogenesis." (PMID 40808640, 2025). "This implies that ETV1 overexpression restrains its own oncogenic impact, at least during the initial PIN phase of prostate tumorigenesis, by causing SMAD3/4 overexpression." (PMID 31160676, 2019). "Considering the co-overexpression of ETV1 and ETV4 in MDA-PCa-2b and PC3 cells, we sought to dissect the role of these ETS in prostate carcinogenesis." (PMID 25595908, 2015). "In summary, this study provides new information on the oncogenic role of ETV1 and ETV4 in prostate carcinogenesis by looking at a co-expression cellular context in vitro." (PMID 25595908, 2015).
gastrointestinal tumours (1 paper, 2020). "Activated KIT is reported to prolong ETV1 protein stability and cooperate with ETV1 to promote tumorigenesis in gastrointestinal tumours." (PMID 32580154, 2020).
genetic disease (1 paper, 2014). "Here, we report the association and positive functional interaction of Pkp3 with a transcription factor, Ets variant gene 1 (ETV1), which has critical roles in neural development and prominent roles in human genetic disease." (PMID 24475179, 2014).
ETV1 also shares sentences with these, for which no sentence is quoted: leukemia (4 papers); acute myeloid leukemia (1); adult T-cell leukaemia (1); anaplastic oligodendroglioma (1); B-cell lymphoma (1); Barrett's metaplasia (1); cardiac hypertrophy (1); cortical dysplasia (1); ductal carcinomas in situ (1); embryonal carcinoma (1); fibrosarcoma (1); gout (1); hyperplasia (1); inflammatory bowel disease (1); invasive breast carcinoma (1); invasive ductal carcinomas (1); Limb ataxia (1); lymphoma (1); major depression (1); medulloblastoma (1); mental disorder (1); metabolic disease (1); myocardial infarction (1); neurological disorder (1); osteosarcoma (1); pilocytic astrocytoma (1); renal cell carcinoma (1); rhabdomyosarcoma (1); schizophrenia (1); schwannoma (1).
A further 4 diseases each share a sentence with ETV1 in 1 paper.